CXCR4 (C-X-C motif chemokine receptor 4)
Diseases named in the same sentence as CXCR4 in open-access papers (continued):
Sharing a sentence is not in itself a finding about the gene and the disease.
multiple myeloma (continued). "As such, CXCR4 is a promising drug target and one CXCR4 antagonizing agent, AMD3100 (Mozobil) has been approved as stem cell mobilizing agent for autologous transplantation in patients with Non-Hodgkin's Lymphoma or multiple myeloma." (PMID 33941197, 2021). "Based on recent clinical research, mostly performed with [68Ga]PentixaFor, CXCR4 is now an established target for PET imaging of hematologic tumors including non-Hodgkin lymphoma, multiple myeloma, chronic lymphocytic leukemia, acute myeloid leukemia and Waldenström macroglobulinemia." (PMID 34683912, 2021). "Since CXCR4 expression is generally high among hematological malignancies, including non-Hodgkin lymphoma (NHL), multiple myeloma (MM), chronic lymphocytic leukemia (CLL) and acute myeloid leukemia (AML), most experience with CXCR4-directed PET imaging is based on patients with these diseases." (PMID 34885030, 2021). "A small CXCR4 antagonist, AMD3100, is currently used in combination with G-CSF (Granulocyte Colony-Stimulating Factor) as stem-cell mobilizing agent to treat non-Hodgkin’s lymphoma and multiple myeloma." (PMID 33125391, 2020). "The CXCR4/CXCL12 axis has been described to regulate the localization of NK cells in the bone marrow and seems to be of importance with respect to recruitment of NK cells to the tumor site in neuroblastoma and multiple myeloma." (PMID 31457007, 2019). "Most experience with CXCR4-directed PET imaging has been gained in MM and around two thirds of patients could overexpress the receptor on the myeloma cell surface." (PMID 31024917, 2019). "The peculiar multiple myeloma microenvironment, characterized by up-regulated levels of several inflammatory chemokines, including the CXCR3 receptor ligands CXCL9 and CXCL10, limits NK cell positioning into the bone marrow by interfering with CXCR4 function." (PMID 31699153, 2019). "We recently showed that the expression of CXCR4 and CXCL12 in multiple myeloma cells is positively regulated by Notch signaling and may be impaired by γ-secretase inhibitors." (PMID 30154786, 2018). "Moreover, exosomes released by multiple myeloma cells increase the viability and migration of osteoclast precursors, through the increasing of CXCR4 (C-X-C chemokine receptor type 4) expression and differentiation." (PMID 29642618, 2018). "Considering that HIF-1α drastically enhances miR-210 levels in myeloma cells, we postulated that HIF-1α may affect expression of CXCR4 and VLA4 through miR-210 activation." (PMID 30108468, 2018). "In recent years, many agents targeting SDF-1 and CXCR4 axis have been developed for clinical use, and one drug, AMD3100 (plerixafor or Mozobil) was approved for mobilization of hematopoietic stem cells in multiple myeloma and non-Hodgkin lymphoma patients." (PMID 26954567, 2016). "Considering the key role of CXCL12 in the localization of NK cells in BM, subversion of the CXCR4/CXCL12 axis has been hypothesized to represent a mechanism of immune evasion from NK-mediated immune surveillance in neuroblastoma and multiple myeloma." (PMID 27766097, 2016). "CXCR4 and its ligand CXCL12 are important in the migration of cells to the lymph nodes in acute lymphoblastic leukemia and chronic lymphocytic leukemia, they are also an important factor for migration of myeloma cells to the bone marrow." (PMID 24859274, 2014). "In myeloma and CLL ibrutinib inhibits CXCR4/SDF1-mediated migration." (PMID 25294819, 2014). "The role of CXCR4/CXCL12 axis has been proved also in hematopoietic neoplasms, such as acute lymphoblastic leukemia (ALL), acute myeloid leukemia (AML), chronic lymphocytic leukemia (CLL), multiple myeloma (MM) and Waldenström Macroglobulinemia (WM)." (PMID 24859274, 2014). "As a specific antagonist of chemokine receptor CXCR4, AMD3100 has been approved in human clinical trials for hematopoietic stem cell mobilization to the peripheral blood in patients with non-Hodgkin’s lymphoma and multiple myeloma." (PMID 24735601, 2014).
multiple myeloma (continued). "Features included demographics, laboratory/genetic variables, and imaging metrics from FDG- and CXCR4-PET, stratified by anatomic site (medullary vs. extramedullary) and concordance (concordant vs. discordant as defined by comparing FDG- and CXCR4-positive myeloma lesions)." (PMID 41706122, 2026). "To target the CXCR4/CXCL12 axis, we used the CXCR4 antagonist Motixafortide (MTF, BL‐8040), which is Food and Drug Administration (FDA)‐approved as a hematopoietic stem cell mobilizer in multiple myeloma, and tested whether combining MTF with CAR T cells potentiates cytotoxicity in our 3D model." (PMID 41368078, 2025). "In vitro experiments showed CXCR4-PEG-CdTe-DOX facilitated intracellular drug accumulation through active CXCR4 targeting and released DOX into the microenvironment in a pH-controlled manner, enhancing the therapeutic efficacy and apoptosis rate of myeloma cells (U266)." (PMID 38244066, 2024). "A few classes of CXCR4 antagonists have undergone clinical trials, including peptide inhibitors, small molecule inhibitors, and monoclonal antibodies such as Plerixafor, which is approved by the Food and Drug Administration (FDA) for the treatment of non-Hodgkin’s lymphoma and multiple myeloma." (PMID 39001265, 2024). "Furthermore, CXCR4 intracellular expression in myeloma cells from BM specimens showed more co-localization with CD138 + cells in bortezomib-naive patients compared with bortezomib-responsive patients, implying that CXCR4 mediates chemo-resistance in MM." (PMID 37798791, 2023). "In contrast, the theory that myeloma plasma cells might directly modify the spleen signal by infiltrating this organ is rather unlikely since we did not observe any correlation between myeloma CXCR4 positivity and SUVpeak of the spleen." (PMID 35966583, 2022). "Three chemokine antagonists have been approved: Maraviroc (a CCR5 antagonist) for anti-HIV treatment, Plerixafor (a CXCR4 antagonist) for the treatment of multiple myeloma or non-Hodgkin’s lymphoma, and Mogamulizumab (a CCR4 antagonist) for the treatment of mycosis fungoides or Sézary syndrome." (PMID 34017692, 2021). "PET imaging with CXCR4 targeted [68Ga]Ga-Pentixafor, another promising radiotracer, enabled detection of myeloma lesions that could not be detected with [18F]FDG and paved way for selecting patients for CXCR4 directed therapies." (PMID 34586539, 2021). "However, reduced expression of cell adhesion molecules like VLA-4, CD44, P-selectin, and CD56, promotion of homing of myeloma cells by decreased expression of chemokine receptors like CCR1, CCR2, and CXCR4, and increased angiogenesis have been proposed as mechanisms." (PMID 31467739, 2019). "Co-incubating NK cells with the MHC Class I positive, NK- sensitive myeloma cell line RPMI-8226 reduced the percentage of CXCR4+ NK cells (mean decrease 50.65% ± 20.38; p = 0.005) without significant change in the expression of other activation receptors compared to unstimulated NK cells." (PMID 31242243, 2019). "Moreover, it has been demonstrated that CD138-myeloma cells, which have elevated expression of SDF-1, induce higher stiffness in MSCs from multiple myeloma patients than in normal MSCs through the induction of SDF-1/CXCR4/AKT signaling." (PMID 27630452, 2016). "The fully human CXCR4 mAb, MDX-1338, was recently shown to effectively block calcium flux and migration of cancer cells, induce apoptosis in various tumor cell lines in vitro and reduce tumor growth in xenograft models of acute myeloid leukemia, non-Hodgkin lymphoma and multiple myeloma." (PMID 26848769, 2016). "Another CXCR4 antagonist, POL6326 has successfully completed Phase I clinical trials and is currently being investigated as a stand-alone therapy in a Phase II clinical trial for its efficacy in autologous transplantation of hematopoietic stem cells in multiple myeloma patients." (PMID 26062132, 2015).
multiple myeloma (continued). "For example, blocking the CXCL12/CXCR4 axis with the CXCR4 antagonist AMD3100 or Plerixafor is clinically approved for the mobilization of hematopoietic progenitor cells in combination with granulocyte-colony stimulating factor (G-CSF) in patients with non-Hodgkin’s lymphoma and multiple myeloma." (PMID 26347749, 2015). "Moreover, intracellular expression of CXCR4 in myeloma PCs from BM biopsy specimens demonstrated higher CXCR4 colocalization with CD138+ cells of non-responder patients to bortezomib compared with responder patients, suggesting that CXCR4 mediated chemoresistance in MM." (PMID 35064098, 2022). "Therefore, the antiangiogenic role of microRNA-15a and –16 may contribute, at least in part, to their anti-MM activityTargeting the SDF1-α/CXCR4 pathway with CXCR4 antagonist AMD3100 can mobilize MM cells in the circulation and render them sensitive to anti-myeloma treatment." (PMID 30002349, 2018). "Likewise, the CXCR4 antagonist TG-0054 (Burixafor, ChemoCentryx) and the aptamer Nox-A12 (Spiegelmer, Noxxon), an anti-CXCL12/SDF-1, are currently being tested in clinical trials in combination with chemotherapy for multiple myeloma and for chronic lymphatic leukaemia." (PMID 26062132, 2015).
lung carcinoma (178 papers, 2008 to 2026). "Reanalysis of single‐cell RNA‐seq data from T cells of lung cancer patients also revealed that upregulation of CXCR4 expression in tumor‐infiltrated CD8+ T cells was linked to TGF‐β‐SMAD signaling." (PMID 41257391, 2026). "Aberrant CXCR4 expression is frequently observed in lung cancer and is closely associated with adverse prognosis, enhanced metastatic potential, and therapeutic resistance." (PMID 41750259, 2026). "A previous study from our group, involving a smaller cohort of lung cancer patients, revealed similar biomarker expression levels, indicating that elevated expression of CXCR4 and JUNB is associated with poorer OS in extended‐stage SCLC." (PMID 39575761, 2025). "The development of these effector functions of lung cancer has been linked to the function of the CXCR4/CXCL12 axis." (PMID 41383468, 2025). "The chemokine CXCL12 along with its receptor, CXCR4, have been implicated in the progression and metastasis of cancers, including lung cancer." (PMID 40589738, 2025). "CXCR4/CXCL12 interactions contributed to the promotion of tumor-initiating cells in lung cancer, which was associated with chemotherapy resistance." (PMID 38363409, 2024). "Fourteen out of 27 studies including 1899 patients with lung cancer evaluated the association between CXCR4 expression and overall survival (OS)." (PMID 35729596, 2022). "Using a fixed-effects model, the results showed that increased CXCR4 expression was associated with reduced DFS in lung cancer (HR 3.39, 95% CI 2.38–4.83, P < 0.001, I2 = 0%)." (PMID 35729596, 2022). "Our subgroup analysis indicated that cytoplasmic and membrane CXCR4 staining conferred a more significant association with poor OS than nuclear CXCR4 staining in lung cancer." (PMID 35729596, 2022). "The CD4+CD25highFoxP3+ regulatory T cells, associated with tumor progression, were shown to express CXCR4 and be recruited into lung cancer." (PMID 35729596, 2022). "The pooled HR showed that high CXCR4 expression was linked to decreased OS in lung cancer (HR 1.61, 95% CI 1.42–1.82, P < 0.001, I2 = 32.2%)." (PMID 35729596, 2022). "In a series of 176 tumor samples from patients with advanced lung cancer, in which CXCR4 was expressed in most tumors, CXCR4 overexpression was associated with significantly poorer survival." (PMID 35740564, 2022). "The increased CXCR4 expression was related to the clinicopathological features of lung cancer, but high heterogeneity was observed for the associations with tumor stage (I2 = 59.0%), distant metastasis (I2 = 77.7%), and TNM stage (I2 = 68.7%)." (PMID 35729596, 2022). "The CXCR4 (chemokine)/CXCL12 (chemokine receptor) interaction helped to promote tumor-initiating cells in lung carcinomas, which was associated with resistance to chemotherapy." (PMID 34745015, 2021). "Surface expression of CXCR4 protein on lung cancer cells harboring the EGFR-L858R mutation (median, 12.61; range: 8.95–34.56) was significantly higher than that in EGFR-WT cells (median, 5.36; range, 2.00–12.58; P = 0.025, Mann-Whitney U Test)." (PMID 26338423, 2015). "In the current study, we reported that CXCR4 surface protein expression in clinical samples from lung cancer patients with tumors expressing the EGFR-L858R mutation is significantly higher than that in tumors expressing EGFR-WT." (PMID 26338423, 2015). "We found that expression of EGFR-L858R in lung cancer cells resulted in up-regulation of the CXCR4 in association with increased cancer cell invasive ability and MPE formation." (PMID 26338423, 2015). "Some of them, namely CXCR4, were also associated with metastasis in other types of neoplasms like breast, prostate, ovarian, colon and lung cancers." (PMID 24559071, 2014). "Expression of CXCR4 in lung cancer has also been linked to longer overall survival and longer disease-free survival for total CXCR4 expression and to longer overall survival for nuclear CXCR4 expression." (PMID 23844053, 2013).
lung carcinoma (continued). "Interestingly, the upregulation of CXCR4 has been linked to an increased rate of migration in lung cancer towards the bone marrow." (PMID 37489388, 2023). "Consequently, JUNB and CXCR4 were expressed in CTCs from lung cancer patients, and associated with patients’ survival, underlying their key role in tumor progression." (PMID 36612166, 2022). "Our results showed that high CXCR4 expression, whether in multivariate analysis or in univariate analysis, was associated with poor survival in patients with lung cancer." (PMID 35729596, 2022). "Because cell invasiveness in vitro reflects metastatic properties in vivo we hypothesized that the inhibition of breast-to-lung cancer metastasis by BD is associated with the downregulation of expression of uPA and CXCR4 in primary tumors." (PMID 22842551, 2012). "Several research works proposed that increased CXCR4 expression was associated with enhanced metastatic potential of lung cancer cells and contributed to increase in their self-renewal activity, which may be key regulator of tumor invasiveness leading to local progression and tumor metastasis." (PMID 28903328, 2017). "This review synthesizes the molecular features, regulatory networks, and translational potential of CXCR4 in lung cancer and discusses future directions for precision therapy and biomarker-guided intervention." (PMID 41750259, 2026). "68Ga-Pentixafor PET/CT, a molecular imaging technique targeting the C-X-C chemokine receptor 4 (CXCR4), has emerged as a promising tool in the diagnosis and therapeutic evaluation of lung cancer." (PMID 42099745, 2026). "Together, these studies have identified CXCR4 as a major player in driving lung cancer progression, metastasis, immune suppression, and chemo-resistant disease, and reinforce that it is a target worthy of precision medicine." (PMID 41383468, 2025). "CXCR4 is known to direct lung cancer cells toward CXCL12-rich metastatic sites such as the bone marrow, liver, and brain, fueling metastatic dissemination." (PMID 41383468, 2025). "Specifically, targeting HuR using siRNA-based nanoparticles plus AMD3100 inhibits C-X-C motif chemokine receptor 4 (CXCR4) and suppresses lung cancer metastasis." (PMID 40271197, 2025). "Over the past years, the CXCR4/CXCL12 cascade has been a significant therapeutic target in lung cancer since it offers a major function in cancer development, metastasis, immunological evasion, and resistance to treatment." (PMID 41383468, 2025). "The role of CXCR4 in lung cancer therapy extends beyond metastasis and resistance, with targeted approaches being actively explored." (PMID 41383468, 2025). "Chemokines, particularly the CCR9/CCL25 and CXCL12/CXCR4 axes, play pivotal roles in lung cancer progression, immune cell recruitment, and tumor microenvironment remodeling." (PMID 40607416, 2025). "In this review, we explore the function of the CXCR4/CXCL12 axis in lung cancer metastasis and its therapeutic potential for stopping tumor progression and strengthening cancer treatment." (PMID 41383468, 2025). "CXCL12 is additionally secreted by stromal fibroblasts, endothelial cells, and immune cells in lung cancer in such amounts that they form chemotactic gradients drawing CXCR4-expressing cancer cells to metastatic niches such as liver, brain, and bone marrow." (PMID 41383468, 2025). "LncRNA00922 accelerates lung cancer cell proliferation, invasion, and metastasis by regulating miRNA204/CXCR4." (PMID 40607416, 2025). "Since CXCR4 is pivotal in the advancement of lung cancer, focusing on this cascade is an ideal treatment strategy." (PMID 41383468, 2025). "High CXCR4 expression in lung cancer correlates not only with cell invasion and metastasis but also with poor prognosis." (PMID 40607416, 2025). "We previously identified JUNB and the chemokine receptor CXCR4 as prognostic biomarkers for breast and lung cancer." (PMID 39575761, 2025).